HSPA12A (heat shock protein family A (Hsp70) member 12A)
Diseases named in the same sentence as HSPA12A in open-access papers (continued):
Sharing a sentence is not in itself a finding about the gene and the disease.
cancer (7 papers, 2017 to 2026). A tumor composed of atypical neoplastic, often pleomorphic cells that invade other tissues. "We next evaluated the correlation between SEC23A expression and MEF2A or Hspa12a in Pan-cancer patients and prioritized MEF2A for biological validation." (PMID 34456965, 2021). "For instance, HSPA12A is known to regulate inflammatory responses, ATP2C2 plays a critical role in immune microenvironment, and NCS1 is associated with immunotherapy and prognosis of cancer." (PMID 41140666, 2025). "When taken into account that we have recently revealed the regulatory roles of HSPA12A in lactate production in cancer cells, we thus hypothesized here that HSPA12A may control lactate homeostasis and thereby modulate neurogenesis and mood stability." (PMID 37580315, 2023). "We counted the numbers of pathways affected by each HSP; the results suggested that HSPA1L, HSPA12B, HSPA6, HSPA7 and HSPA12A may influence the activity of most cancer-related pathways and thus potently affect tumor development." (PMID 34712697, 2021). "To address the role of HSPA12A in RCC pathogenesis, we first analyzed Hspa12a mRNA expression by mining The Cancer Genome Atlas (TCGA) database for Kidney Renal Clear Cell Carcinoma (KIRC)." (PMID 32754264, 2020). "In this study, several of the differentially expressed molecules identified, including TGFBI, NES, SNCA, and HSPA12A, have demonstrated roles in GBM and other cancers." (PMID 29228611, 2017). "Overlapping molecules in two groups included up-regulated transforming growth factor beta induced (TGFBI) and Nestin (NES); and down-regulated synuclein alpha (SNCA) and heat shock protein family A member 12A (HSPA12A), which have demonstrated roles in GBM and/or other cancers." (PMID 29228611, 2017).
infection (4 papers, 2020 to 2023). The state of being infected such as from the introduction of a foreign agent such as serum, vaccine, antigenic substance or organism. "Diets did not significantly affect brain hspa12a mRNA levels in uninfected fish (p > 0.05), but there was a significant interaction between diet and infection." (PMID 37958062, 2023).
tumor (3 papers, 2017 to 2023). "In this study, we found that RCC tumors from patients showed downregulation of HSPA12A, which was associated with advanced tumor node metastasis (TNM) stage and Fuhrman grade." (PMID 32754264, 2020). "Reduced HSPA12A expression was significantly associated with advanced TNM stage, high Fuhrman grade, and large tumor size." (PMID 32754264, 2020). "In the present study, we detected a downregulated expression of HSPA12A in human RCC tumors, which was associated with advanced TNM stage and Fuhrman grade, as well as larger tumor size." (PMID 32754264, 2020). "We found that human RCC tumors with lower HSPA12A expression showed significantly higher MCT4 protein expression than their corresponding non-tumor counterparts." (PMID 32754264, 2020). "Finally, the Ptprd (FC −3.18) and Ptprr (FC −3.25) tumor suppressor genes showed a lower expression in technological cells, whereas the Hspa12a heat shock protein was significantly up-regulated (FC 3.09)." (PMID 29078721, 2017). "Furthermore, for the same group, we found up-regulation of Hspa12a, whose high expression has been proven in tumor tissues." (PMID 29078721, 2017).
psychiatric diseases (2 papers, 2019 to 2023). "As genome sequencing studies grow larger, it will become clear if rare variants in HSPA12A are part of the pathogenesis of Alzheimer’s or other psychiatric diseases." (PMID 30679749, 2019). "Moreover, the causal effects of HSPA12A in any psychiatric disorders are completely unknown." (PMID 37580315, 2023). "However, the causal effects of HSPA12A in any psychiatric disorders are completely unknown." (PMID 37580315, 2023). "The role of HSPA12A and its interplay with SorLA in the pathogenesis of psychiatric diseases remains to be determined." (PMID 30679749, 2019).
movement disorder (1 paper, 2025). Neurological conditions resulting in abnormal voluntary or involuntary movement, which may impact the speed, fluency, quality and ease of movement. "Recessively inherited cases with consistent neurodevelopmental and movement disorder phenotypes similar to CP were identified for four genes (HSPA12A, SLC7A1, TP53BP1, WWC1)." (PMID 41282771, 2025).
neurodegenerative disease (1 paper, 2019). A disorder of the central nervous system characterized by gradual and progressive loss of neural tissue and neurologic function. "The identification of the relatively unknown HSPA12A as a SorLA specific interaction partner could lead to novel insight into the molecular mechanism of SorLA, and re-emphasises the role of heat shock proteins in neurodegenerative diseases." (PMID 30679749, 2019).
HSPA12A also shares sentences with these, for which no sentence is quoted: glioma (2 papers); renal cell carcinoma (2); attention deficit-hyperactivity disorder (1); autism (1); autoimmune disease (1); bipolar disorder (1); bladder urothelial carcinoma (1); colon cancer (1); endometrial cancer (1); endotoxemia (1); hyperlipidemia (1); liver cancer (1); lung carcinoma (1); overdose (1); periodontitis (1).